HNF4A (hepatocyte nuclear factor 4 alpha)
Diseases named in the same sentence as HNF4A in open-access papers (continued):
Sharing a sentence is not in itself a finding about the gene and the disease.
liver cancer (87 papers, 2011 to 2026). An epithelial or non-epithelial malignant neoplasm that arises from the liver. "The HNF4α downregulation in liver cancer was also associated with EMT progression and poor prognosis." (PMID 41244070, 2025). "In this review, we summarized the possible mechanisms associated with HNF4α and HNF1α that regulate multiple oncogenic pathways in the liver and discussed the potential use of HNF4α as a therapeutic target for liver cancer." (PMID 34771521, 2021). "High-throughput analysis of cancer cell genomes has identified a number of hotspot mutations in HNF1α and HNF4α in liver cancer." (PMID 34771521, 2021). "High-throughput analysis of cancer cell genomes has established that hotspot mutations in HNF4α and HNF1α occur in a variety of human cancers, including liver cancer." (PMID 34771521, 2021). "Conversely, genetic or metabolic restoration of the transsulfuration pathway in SAA metabolism significantly alleviates the outcomes induced by HNF4α deficiency in liver cancer cells." (PMID 32770044, 2020). "Our study presents several liver cancer-related HNF4A mutations that lead to alterations in DNA binding and/or transcription activity." (PMID 29899848, 2018). "We found that low HNF4A expression was associated with worse prognosis in liver cancers (p-value < 0.05)." (PMID 29899848, 2018). "In our whole genome sequencing analysis, we found seven somatic mutations (three Zn-finger mutations, three deletion mutants, and one intron mutation) of HNF4A in liver cancers." (PMID 29899848, 2018). "Furthermore, liver cancer cells deficient in HNF4A-liver-TEs exhibited diminished growth capacity both in vitro and in vivo." (PMID 38965210, 2024). "In contrast to hyperlipidemia in NAFLD, hypolipidemia often occurs in patients with end-stage liver diseases, such as cirrhosis and liver cancer, in which the loss of functional HNF4α is more marked and may be better mimicked by the use of HNF4α KO mice." (PMID 35614477, 2022). "Our group identified, for the first time, functional HNF4α mutations in liver cancers." (PMID 34771521, 2021). "Therefore, identifying pathogenic mutations of HNF1α and HNF4α has implications for liver cancer biology and drug targets for precision medicine." (PMID 34771521, 2021). "Therefore, HNF4α deficiency in epithelial liver cancer cells results in a global metabolic shift towards mesenchymal liver cancer cells." (PMID 32770044, 2020). "Our findings may pave the way for therapeutic strategies against liver cancer and other HNF4α-associated human cancers." (PMID 32770044, 2020). "Thus, we here focused on the functional analysis of HNF4A mutations in liver cancers, namely HNF4A G79C, F83C, and M125I, which are in the Zn-finger DNA binding domain of HNF4A." (PMID 29899848, 2018). "Our current study identifies for the first time functional HNF4A mutations in liver cancers." (PMID 29899848, 2018). "Additionally, our group reported for the first time that HNF4A G79C, F83C, and M125I mutations are loss-of-function mutations found in liver cancer patients, leading to a reduction in HNF1A gene expression and concomitantly, an increased risk of HCC development." (PMID 35327967, 2022). "Therefore, we propose that HNF4A mutations G79C, F83C, and M125I are functional mutations found in liver cancers and that loss of HNF4A function, through its mutation, leads to a reduction in HNF1A and ApoB gene expression with a concomitant increased risk of liver tumorigenesis." (PMID 29899848, 2018). "Therefore, it is possible that mutations at evolutionary conserved positions in HNF4A Zn-finger region and ligand domain may augment risk of triggering liver cancer development." (PMID 29899848, 2018). "Hepatocyte nuclear factor 4 alpha (HNF4α), another liver-specific PTF, is disrupted by HBV and implicated in liver cancer progression." (PMID 40589575, 2025).
liver cancer (continued). "In conclusion, this study uncovers a liver-TE/KDM1A/HNF4A regulatory axis that promotes liver cancer growth and highlights KDM1A as a promising therapeutic target." (PMID 38965210, 2024). "To identify liver cancer suppressor genes related to liver-TE that are controlled by KDM1A-mediated HNF4A repression, we focused on MAT1A, a known HNF4A target gene associated with liver-TE which is directly repressed by KDM1A." (PMID 38965210, 2024). "The liver-TE/KDM1A/HNF4A regulatory loop exemplifies the intricate interplay between these factors in liver cancer development and progression." (PMID 38965210, 2024). "Our study emphasizes the critical role of KDM1A in regulating liver cancer cell growth through two mechanisms involving HNF4A." (PMID 38965210, 2024). "HNF4A, a member of the nuclear receptor superfamily, serves as a pivotal regulatory factor in the initial stages of liver cancer development." (PMID 38965210, 2024). "This suggests that KDM1A downregulates the activity of the HNF4A-regulated hepatocyte-specific methionine metabolic pathway, ultimately promoting liver cancer." (PMID 38965210, 2024). "Through the use of CRISPR/Cas9 technology, we selectively removed liver-TEs located within the transcriptional regulatory region of the HNF4A gene (HNF4A-liver-TEs) in liver cancer cells." (PMID 38965210, 2024). "A study implicates HNF4A as the top upstream regulator of metabolism in liver cancer, particularly in a subtype of cholangiocarcinoma with high HNF4A and genes related to bile acid metabolism." (PMID 38255993, 2024). "Pan-cancer expression profiling showed that MAT1A is liver tissue-specific, highly expressed in normal liver and liver cancer tissues, but downregulated in liver cancers compared to normal liver tissues, a pattern exemplifies HNF4A downstream signature." (PMID 38965210, 2024). "HIC1 acts as a tumor suppressor inhibiting cell growth, migration, and survival; on the other hand, HNF4A is critical for liver development and is upregulated in liver cancer." (PMID 37132605, 2024). "Our findings reveal that the expression of HNF4A is inversely regulated by proximate liver-TEs, which facilitates liver cancer cell proliferation." (PMID 38965210, 2024). "We found that the restrained in vitro and in vivo cell growth caused by KDM1A knockdown was partially restored by HNF4A downregulation, indicating that KDM1A promotes the growth of liver cancer cells by inhibiting the expression of HNF4A." (PMID 38965210, 2024). "For example, liver-CASs were enriched with motifs of HNF4a and PPARa, which are vital TFs for the development of liver cancer." (PMID 37283809, 2023). "Knockdown of HNF4α in HNF4α-positive epithelial liver cancer cells promotes EMT and induces cell migration." (PMID 37772039, 2023). "Increased HNF4α expression in liver tissues attested liver cancer cell differentiation induced by SMC treatment." (PMID 35343115, 2022). "Given that previous study already reported that overexpression of HNF4α would lead to differentiation of liver cancer cells, the staining results indicated that SMC effectively abrogated liver tumors by inducing cancer cell differentiation in vivo." (PMID 35343115, 2022). "The role of SHP in mediating the inhibitory effects of HNF4α on hepatic lipogenesis, inflammation, and liver cancer warrants further investigation." (PMID 35614477, 2022). "The important role of HNF4α in development and metabolism, especially in liver tissues, led to the initial research focusing on HNF4α in liver cancer." (PMID 36249028, 2022). "In the progression of liver cancer,HNF4α is regulated by factors such as STAT3 and KAT2B, and function as tumor suppressor through HSD17B6, HNF1α, FOXAs, MARC2." (PMID 36249028, 2022). "Researches about HNF4A in cancer mostly focused on liver cancer, and HNF4A mainly functions as a tumor suppressor in liver cancer." (PMID 35132353, 2022).
liver cancer (continued). "The Snail1 suppression resulted in HNF4α activation which promoted the restoration of hepatic features in remaining living liver cancer cells." (PMID 35343115, 2022). "Despite ample evidence suggesting HNF4α acts as a tumor suppressor in liver cancer, its role in other types of cancers is still unclear." (PMID 34771521, 2021). "It covers the molecular mechanisms of HNF1α and HNF4α dysregulation and also highlights the potential of HNF4α as a therapeutic target in liver cancer." (PMID 34771521, 2021). "Here, we review recent findings pertaining to role of HNF1α and HNF4α in liver cancer, and their possible targeting for liver cancer treatment." (PMID 34771521, 2021). "In this review, we update current findings on the roles of HNF1α and HNF4α in liver cancer development and progression." (PMID 34771521, 2021). "Many studies have focused on liver cancer because of the pivotal role of HNF4α in the normal physiology and development of the liver." (PMID 34771521, 2021). "BMAL1 and HNF4A ChIP-seq signals from human liver cancer Hep3B or HepG2 cells were plotted correspondingly at each position of the BMAL1 binding sites we just profiled in U2OS-GFP and U2OS-HNF4A2 cells." (PMID 34732735, 2021). "HNF4α plays a role throughout the initiation, malignant transformation, and metastasis in liver cancer development by regulating the key events of inflammation, epithelial–mesenchymal transition (EMT), and the differentiation status of the cells." (PMID 34771521, 2021). "This STAT3 expression is negatively correlated with HNF4α, and stress-induced activation of the STAT3–HNF4α inflammatory loop leads to the decreased expression of miR-122, which is responsible for liver cancer cell migration and invasion." (PMID 34771521, 2021). "Based on RNA-seq analysis, ectopic expression of FOXA3, HNF1A, and HNF4A resulted in expression levels in iHeps that are comparable to those observed in liver cancer cell lines." (PMID 34302118, 2021). "Here we report that hepatocyte nuclear factor 4α (HNF4α) dictates the sensitivity of liver cancer to methionine restriction." (PMID 32770044, 2020). "In this study, we show that the heterogenous response of liver cancer cells to methionine restriction is due to, at least partially, their distinct HNF4α status." (PMID 32770044, 2020). "Our study has important translational implications as it identifies HNF4α as a potential biomarker for liver cancer patient selection in prospective clinical trials of dietary interventions with methionine restriction." (PMID 32770044, 2020). "The emergence of stem cells promotes drug resistance in liver cancer cells after PRMT5 suppressed the expression of HNF4α." (PMID 32859239, 2020). "Our study identifies HNF4α as a regulator of hepatic SAA metabolism that regulates the sensitivity of liver cancer to methionine restriction." (PMID 32770044, 2020). "In our previous studies, we found that ferroptosis is more likely to be inhibited in liver cancer cells because the transcriptional signaling pathway controlled by HNF4A corresponds to a series of ferroptosis-resistant molecules." (PMID 33372599, 2020). "OF activates phosphorylation of STAT3 and enhances the binding to P1‐promoter of HNF4A which is the potential mechanism for reducing hepatocarcinogenesis in liver cancer." (PMID 33377648, 2020). "Knockdown of HNF4α in epithelial liver cancer cells led to an impaired SAA metabolism that closely resembles mesenchymal liver cancer cells." (PMID 32770044, 2020). "Collectively, our findings not only identify a genetic master regulator of SAA metabolism, but also demonstrate that HNF4α-mediated transsulfuration is a key determinant of sensitivity to methionine/cystine restriction in liver cancer." (PMID 32770044, 2020). "This was also reflected by heterogeneous induction of the cholangiocyte marker pan-CK and inhibition of HNF4α in our AKT/HES5-liver cancer mouse model." (PMID 32055024, 2020).
liver cancer (continued). "Together, our data indicate that HNF4α controls SAA metabolism in liver cancer cells through transcriptional regulation of the expression of SAA enzymes." (PMID 32770044, 2020). "On the other side, HNF4α is able to negatively control YAP activity in liver cancer cells by competing with YAP for TEAD4 binding." (PMID 31601778, 2019). "Our results reveal that the two isoforms of HNF4α (“P1-HNF4α” and “P2-HNF4α”), which are differentially expressed in liver cancer, exhibit distinct circadian roles." (PMID 30341289, 2018). "This suggests that HNF4A modulates not only liver tissue differentiation but also liver cancer cell fate." (PMID 29899848, 2018). "Although conflicting reports have assigned HNF4α tumor-promoting role in liver cancer, our data support the tumor-suppressing role of HNF4α in line with other reports." (PMID 29983862, 2018). "In this regard, we identified reduced HNF4A mRNA and protein expressions in undifferentiated liver cancer cell lines." (PMID 29899848, 2018). "Similar to our findings, HNF4A and several HNF4A target genes were down-regulated in liver cancer patients." (PMID 30463528, 2018). "In fact, our data demonstrates that HNF4A mRNA expression is lower in undifferentiated liver cancer cells (aggressive cancer cells)." (PMID 29899848, 2018). "Future study on the use of the CRISPR-Cas9 system to specifically enhance the protein expression of P1- HNF4α to treat liver cancer is warranted." (PMID 29234104, 2017). "To investigate if HNF4α directly regulates PED expression, we reduced HNF4α expression by siRNA in two different liver cancer cell lines (HuH-7 and PLC/PRF-5)." (PMID 29072691, 2017). "For instance, as remarked earlier, HNF4A is a TF which is needed for liver specification, silencing of it leading to liver cancer, yet it is also expressed in other tissue types such as kidney and stomach." (PMID 27562343, 2016). "Using primers specific for ChREBP-α or ChREBP-β and those common for ChREBP-α and ChREBP-β, we found that HNF-4α increased mRNA levels of ChREBP-α, ChREBP-β and total ChREBP in 293T and liver cancer HepG2 cells." (PMID 27029511, 2016). "Ectopic HNF-4α expression increased ChREBP transcription while knockdown of HNF-4α greatly reduced ChREBP mRNA levels in liver cancer cells and mouse primary hepatocytes." (PMID 27029511, 2016). "Another study identified a targetable proinflammatory loop consisting of miR-24/miR-629/HNF-4α/miR-124/STAT3, and revealed that the transient silencing of HNF-4α in cell xenografts maintained low levels of HNF-4α in liver cancers." (PMID 25663852, 2015). "We demonstrated that HNF4A is a liver cancer suppressor gene negatively regulated by liver-TEs." (PMID 38965210, 2024). "To test this hypothesis, we conducted Co-IP experiments and confirmed that endogenous KDM1A interacts with HNF4A in liver cancer cells." (PMID 38965210, 2024). "Similarly, the application of SP2509, a KDM1A inhibitor, heightened HNF4A expression in liver cancer cells." (PMID 38965210, 2024). "Furthermore, our findings highlight the critical function of KDM1A in the growth of liver cancer cells through liver-TE-mediated mechanisms, specifically by repressing the transcriptional activity of HNF4A." (PMID 38965210, 2024). "To ascertain whether the promoting effect of KDM1A on liver cancer depends on its regulation of HNF4A, we simultaneously silenced KDM1A and HNF4A in liver cancer cells." (PMID 38965210, 2024). "The suppression of HNF4A mediated by KDM1A promotes liver cancer cell proliferation." (PMID 38965210, 2024). "For comparison, we have included one high and one low-HNF4A–expressing liver cancer cell lines." (PMID 39165427, 2024). "The role of HNF4α in circadian regulation in liver cancer has also been examined." (PMID 37600688, 2023). "Interestingly, induced expression of BMAL1 in HNF4α-positive liver cancer cells impairs growth in culture and in vivo." (PMID 37600688, 2023).
liver cancer (continued). "HNF4A is critical for liver development, and is up-regulated in liver cancer." (PMID 36105219, 2022). "HNF4α was shown to play an inhibitory role in the development of liver cancer, and was significantly correlated with genes related to drug absorption, distribution, metabolism and excretion in patients with liver cancer." (PMID 36249028, 2022). "In addition, the loss of HNF4A reduced ApoB and HNF1A expression and promoted tumor growth, especially in liver cancer." (PMID 36213507, 2022). "HNF4a is a clock gene that is mainly studied in the field of liver cancer." (PMID 33628089, 2021). "Therefore, identifying a link between their loss-of-function mutations and the molecular mechanism for tumorigenesis will help to improve understanding of how HNF4α and HNF1α function in liver cancer." (PMID 34771521, 2021). "Moreover, HNF4α was reported to induce liver cancer cell proliferation and migration, whereas pituitary homeobox 1 (PITX1) exerted tumor suppressor effects in HCC." (PMID 34409028, 2021). "It has been shown that HNF4a can not only reduce or inhibit cell proliferation but can also accelerate the differentiation speed of poorly differentiated liver cancer by re-expressing HNF4a in liver cancer and maintaining a highly differentiated phenotype, which reduces its invasiveness 9-11." (PMID 33628089, 2021). "Additionally, the knockdown of HNF4α led to substantial reductions in HNF1α and APOB, and RNA-seq data from liver cancer patients also showed that the expression of HNF4α, HNF1α, and APOB mRNA are significantly correlated." (PMID 34771521, 2021). "Neither CYP2D6 nor HNF4A had SNPs related to the health disparity between the two ethnic groups obviating the implication of CYP2D6 polymorphism in the inequalities of liver cancer in AS and CA." (PMID 34597305, 2021). "We further show that overexpression of enzymes or supplementation of key metabolites in the transsulfuration pathway of SAA metabolism significantly restores the sensitivity of HNF4α-depleted liver cancer cells to methionine/cystine restriction or sorafenib treatment and inhibits cell migration." (PMID 32770044, 2020). "Moreover, functional restoration of CBS activity in HNF4α-depleted liver cancer cells, either by supplementation of Ctt or H2S or by overexpression of CBS, significantly alleviates stress resistance, cell migration, and EMT induced by HNF4α deficiency." (PMID 32770044, 2020). "Our data further suggest that the transsulfuration pathway in SAA metabolism, particularly CBS-mediated production of Ctt and H2S, may be one of the major effectors of HNF4α-mediated EMT suppression in liver cancer." (PMID 32770044, 2020). "In addition, there have been reports that PRMT5 and H4R3me2s bind to the promoter region of the hepatocyte nuclear factor 4α (HNF4α) gene in liver cancer cells." (PMID 32859239, 2020). "Therefore, the expression of key SAA metabolic enzymes is positively correlated with that of HNF4α in both liver cancer patients and liver cancer cell lines." (PMID 32770044, 2020). "Moreover, a transcriptional regulatory network has been identified in liver cancer cells, in which the transcription factor (TF) hepatocyte nuclear factor 4 alpha (HNF4A) modulates the transcription of a series of anti-ferroptotic molecules." (PMID 33372599, 2020). "Our whole genome sequencing analysis of liver cancers identified HNF4A as a driver gene candidate." (PMID 29899848, 2018). "HNF4A is also a master regulator of liver-specific gene expression, and these target genes are involved in intermediary metabolism, xenobiotic and drug metabolism, and liver cancer." (PMID 29899848, 2018). "Thus, down-regulation of HNF4α is a major contributing factor to cirrhosis and liver cancer, whereas restoration of HNF4α can inhibit the development of the liver cancer and improve liver function simultaneously." (PMID 29234104, 2017). "Therefore, our experiments indicate that HNF4α regulates cell migration through PED in liver cancer cells." (PMID 29072691, 2017).